P2RY6 (pyrimidinergic receptor P2Y6)
Diseases named in the same sentence as P2RY6 in open-access papers:
P2RY6 is named in the same sentence as 101 diseases in open-access papers, as found by Europe PMC text mining. Sharing a sentence is not in itself a finding about the gene and the disease. The quoted sentences say what the papers report.
Obesity (7 papers, 2017 to 2024). Accumulation of substantial excess body fat. "P2RY6, a receptor for nucleotide uridine 5′ -diphosphate, has been implicated in various human diseases, including obesity and autoimmune diseases." (PMID 36253874, 2022).
Parkinson disease (5 papers, 2017 to 2021). A progressive degenerative disorder of the central nervous system characterized by loss of dopamine producing neurons in the substantia nigra and the presence of Lewy bodies in the substantia nigra and locus coeruleus. "P2ry6 gene expression levels were elevated in monocytes from Parkinson’s disease patients, and expression was increased in a microglial cell line treated with LPS." (PMID 34635136, 2021).
ischemic stroke (4 papers, 2020 to 2022). A stroke disorder caused by obstruction of blood flow to the brain, due to thrombotic (local blood clot formation) or embolic (due to a blood clot or other material traveling from another site) event. "In accordance with that idea, previous studies have shown that blocking of P2RY6 is beneficial in models of AD, PD and ischemic stroke." (PMID 36203578, 2022).
status epilepticus (4 papers, 2018 to 2023). Status epilepticus is defined as a continuous seizure lasting more than 30 min, or two or more seizures without full recovery of consciousness between any of them. "Both, intraamygdala KA and intraperitoneal pilocarpine-induced status epilepticus increased the transcription of the uridine-sensitive P2Y receptors P2ry2, P2ry4, and P2ry6 in the hippocampus." (PMID 29563872, 2018). "Status epilepticus: Increased P2ry2, P2ry4, and P2ry6 and decreased P2ry1, P2ry12, P2ry13, and P2ry14 transcript levels; increased P2Y1, P2Y2, P2Y4, and P2Y6 and decreased P2Y12 protein levels." (PMID 29563872, 2018). "Analysis of the hippocampus 14 days-post status epilepticus revealed increased P2ry1, P2ry2, and P2ry6 transcription and increased P2Y1, P2Y2, and P2Y12 protein levels." (PMID 29563872, 2018).
colon cancer (3 papers, 2017 to 2025). "In addition, P2RY6 protects colon cancer cells from TNF-α-induced apoptosis by activating AKT-mediated phosphorylation of the X-linked inhibitor of apoptosis protein (XIAP)." (PMID 41383622, 2025). "For instance, P2RY6 has been shown to promote skin cancer development by modulating MAPK/ERK1-mediated Hippo/YAP and Wnt/β-catenin signaling, and to enhance migration in lung and colon cancer via the Rho/ROCK pathway." (PMID 41383622, 2025).
colorectal tumor (2 papers, 2022 to 2024). "In contrast, P2RY6 was found to increase the resistance of tumor cells to chemical drugs in colorectal tumors, which is closely related to P2RY6 blocking the apoptotic process and contributing to the persistent development of colorectal tumor cells." (PMID 38180750, 2024).
lung adenocarcinoma (2 papers, 2023 to 2025). A carcinoma that arises from the lung and is characterized by the presence of malignant glandular epithelial cells. "P2RY6 has been reported as a prognosis biomarker in lung adenocarcinoma patients and is associated with the immune microenvironment." (PMID 40066453, 2025). "However, the role of P2RY6 in lung adenocarcinoma (LUAD) remains unknown." (PMID 37880703, 2023).
pancreatic cancer (2 papers, 2017 to 2023). "While previous research has investigated the role of P2RY6 in pancreatic cancer and colorectal cancer, there is currently no corresponding article exploring its role in LUAD." (PMID 37880703, 2023).
bladder cancer (1 paper, 2023). "Furthermore, a higher expression of P2RY6 predicted worse survival in patients with bladder cancer in the TCGA database." (PMID 37313656, 2023).
chronic myelomonocytic leukaemia (1 paper, 2019). "The role of P2RY6 in autophagy regulation was further supported by data showing that the P2RY6 ligand UDP and the specific P2RY6 agonist MRS2693 can restore normal monocyte differentiation through reactivation of autophagy in primary myeloid cells of chronic myelomonocytic leukaemia (CMML) patients." (PMID 30704144, 2019).
kidney cancer (1 paper, 2024). Primary or metastatic malignant neoplasm involving the kidney. "P2RY2, P2RY6, and P2RY11 are three Purinergic genes that we believe are closely related to KIRC but are currently less studied about kidney cancer." (PMID 38180750, 2024).
lung carcinoma (1 paper, 2020). "Next, we determined the expression levels of P2X sub-families P2RX1–7 and P2Y receptors P2RY1, P2RY2, P2RY4, P2RY5 (LPAR6), P2RY6, P2RY7 (LTB4R), P2RY8, P2RY9 (LPAR4), P2RY10–14 in normal lung tissues and lung cancer tissues." (PMID 32638267, 2020).
tauopathy (1 paper, 2021). Neurodegenerative disorders involving deposition of abnormal tau protein isoforms (tau proteins) in neurons and glial cells in the brain. "We found that double-transgenic (P2ry6−/−:P301S+/+) mice had the same severe spinal cord pathology as P301S (P2ry6+/+:P301S+/+) mice, which suggests a different mechanism or severity of neurodegeneration in the spinal cord from the brain in this model of tauopathy." (PMID 34965424, 2021).
thyroid carcinoma (1 paper, 2023). "Our findings revealed a significant increase in the expression level of P2RY6 in stages III–IV of BLCA (bladder urothelial carcinoma) and THCA (thyroid carcinoma)." (PMID 37880703, 2023).
tumor (18 papers, 2013 to 2025). "In our study, elevated P2RY6 expression was associated with higher tumor grade and worse prognosis, consistent with EFFscore-based stratification." (PMID 41383622, 2025). "Although P2RY6 has been implicated in tumor progression across various cancers, its endogenous function and underlying mechanisms in PDAC remain poorly defined." (PMID 41383622, 2025). "As a GPCR activated by extracellular UDP, P2RY6 has been implicated in diverse tumor-promoting processes." (PMID 41383622, 2025). "Second, both our findings and previous studies underscore the critical role of P2RY6 in myeloid and tumor cells; however, its function in other tumor microenvironmental components remains largely unexplored." (PMID 41383622, 2025). "Consistently, tumor growth was significantly inhibited in tumor xenograft model with P2RY6 knockdown." (PMID 41383622, 2025). "Collectively, these findings suggest that additional studies are warranted to delineate the complex mechanisms by which tumor-intrinsic P2RY6 contributes to PDAC progression." (PMID 41383622, 2025). "We discovered five tumor antigens (P2RY6, PLA2G2D, RBM47, SEL1L3, and SPIB) that are significantly increased and mutated, which correlate with the survival of patients and the presence of immune cells that present these antigens." (PMID 40066453, 2025). "Consistently, IHC staining of clinical specimens demonstrated significantly higher P2RY6 expression in tumor tissue than normal pancreatic tissue, which was strongly associated with reduced OS." (PMID 41383622, 2025). "P2RY6 knockdown exerted anti-tumor effects by enhancing ERS and the MHC antigen presentation pathway." (PMID 41383622, 2025). "The EFFscore comprises three genes—ADAM9, P2RY6 and CD36—all of which have been closely associated with tumor progression." (PMID 41383622, 2025). "Functional studies demonstrate that P2RY6 inhibition exhibits tumor-suppressive effects by activating the endoplasmic reticulum stress and enhancing anti-tumor immune responses." (PMID 41383622, 2025). "Transfer of wild-type macrophages to tumor-bearing P2ry6ΔMy mice was sufficient to abrogate the inhibitory effect of myeloid cell-specific P2y6 deletion on tumor growth, highlighting P2Y6 in macrophages as a key regulator of ICB resistance." (PMID 38844817, 2024). "P2ry6 levels were again found to be much higher in TAMs than in TANs, and deletion of P2ry6 was almost complete in sorted TAMs from tumor-bearing P2ry6ΔMy mice and less efficient in TANs." (PMID 38844817, 2024). "In this study, we noted higher expression of the P2RY6 gene in tumor tissues, while IHC showed that the P2Y6 receptor was expressed both in the stroma and tumor cell membrane." (PMID 38773214, 2024). "Although there appears to be a correlation between P2RY6 expression and tumor stage, further evidence is required to clarify the relationship between P2RY6 and tumor progression." (PMID 37880703, 2023). "From these, we can also explain why the increased level of Treg cell infiltration in tumor microenvironment often leads to worse prognosis of patients with high expression of P2RY6." (PMID 37880703, 2023). "Considering the limited number of normal samples in the TCGA database, we decided to further analyze the expression level of P2RY6 in different types of cancers using TCGA’s tumor tissue data and the normal tissue data from the GTEx database." (PMID 37880703, 2023). "The expression of P2RY6 in the LUAD tumor microenvironment is cell-specific, being highest in myeloid cells and endothelial cells and almost absent in NK cells and MAST cells." (PMID 37880703, 2023). "To further explore the mechanisms of P2RY6 in the LUAD tumor microenvironment, we performed a cellular communication analysis." (PMID 37880703, 2023). "The results of this study provide novel insights into the function of P2RY6 in LUAD and elucidate the intrinsic mechanisms by which P2RY6 influences the tumor microenvironment." (PMID 37880703, 2023).
tumor (continued). "Tissue microarray and immunohistochemistry were employed to assess the expression of P2RY6 in internal tumor samples." (PMID 37880703, 2023). "We have also explored the potential role of P2RY6 in tumor immunology and its prognostic value in LUAD." (PMID 37880703, 2023). "Furthermore, the evidence and mechanistic basis for the proposed tumor-suppressive role of P2RY6 by ERS and immunoregulation remain limited, necessitating more well-controlled experiments to substantiate these findings." (PMID 41383622, 2025). "In addition, recent studies indicate that tumor-intrinsic P2RY6 also exerts oncogenic effects and correlates with poor prognosis." (PMID 41383622, 2025). "Tumor-intrinsic P2RY6 has been shown to activate the GNAQ/GNA11–PLCB pathway." (PMID 41383622, 2025). "Beyond these tumor-intrinsic oncogenic effects, emerging evidence suggests that P2RY6 may also facilitate immune evasion." (PMID 41383622, 2025). "Moreover, P2RY6 expression positively correlated with tumor grade, showing higher P2RY6 expression in poorly differentiated tumors." (PMID 41383622, 2025). "EGR1, a transcription factor involved in growth and differentiation, and P2RY6, a receptor gene involved in immune and inflammatory responses, indicate significant transcriptional changes in platelets potentially aiding tumor manipulation of the host environment." (PMID 39001461, 2024). "The results of Cox regression analysis indicated that elevated P2RY6 expression was closely related to poor OS, PFI, and DSS, suggesting that it may serve as a risk factor for most tumor patients (all p < 0.05)." (PMID 37880703, 2023). "Inspired by this, we think that P2RY6 may have a good prospect in the immune regulation of tumor microenvironment." (PMID 37880703, 2023). "Furthermore, these findings underscore the potential utility of P2RY6 in tumor immunotherapy applications." (PMID 37880703, 2023). "Based on these results, we speculate that P2RY6 might play a role in the chemotactic recruitment of immune cells and the regulation of immune signaling pathways in the tumor immune response." (PMID 37880703, 2023). "Importantly, we found that inhibition of ERS did not fully restore the biological function of PDAC, suggesting that P2RY6 may promote tumor progression through additional mechanisms." (PMID 41383622, 2025). "Emerging evidence indicates that PDAC cells promote the infiltration and immunosuppressive activation of P2RY6+ macrophages, suggesting that both tumor and immune cells within the PDAC microenvironment may exploit P2RY6 signaling to facilitate tumor progression." (PMID 41383622, 2025). "Moreover, our bioinformatic analyses in individuals with cancer demonstrate that CDA levels are highest in 11 different tumor types with immunosuppressive features (that is, high in P2RY6, MRC1 and MSR1 levels in macrophages and low in IFNG and PRF levels in CD8+ T cells)." (PMID 38844817, 2024). "As a Gq protein-coupled receptor, P2RY6 has been reported to activate multiple oncogenic signaling pathways, including MAPK, NF-κB, PI3K/Akt and Rho/ROCK, which contribute to tumor cell proliferation, migration, survival, and invasion." (PMID 41383622, 2025). "An efferocytosis-based prognostic model, EFFscore, developed based on ADAM9, P2RY6, and CD36, can effectively assess the tumor phenotype of PDAC patients." (PMID 41383622, 2025). "P2RY6 serves as a key oncogenic factor driver in PDAC, its targeted inhibition significantly suppresses tumor progression, highlighting its dual potential as a diagnostic biomarker and therapeutic target." (PMID 41383622, 2025). "RT-qPCR and WB analyses revealed that P2RY6 expression was markedly upregulated in both PDAC cell lines and tumor tissues compared to normal controls." (PMID 41383622, 2025). "Transcriptomic analysis indicates that P2RY6 knockdown exerts tumor-suppressive effects through excessively activating the endoplasmic reticulum stress (ERS) and enhancing anti-tumor immune responses." (PMID 41383622, 2025).
tumor (continued). "The role of P2RY2, P2RY6, and P2RY12 receptors in gastrointestinal tumors has been reported, including involvement in tumor cell proliferation, metabolism, proliferation, apoptosis, and chemotherapy drug resistance." (PMID 34494914, 2021). "Therefore, before applying our model to clinical practice, further in vivo and in vitro studies are necessary to confirm the interaction between P2RY6 and the LUAD tumor microenvironment." (PMID 37880703, 2023).
cancer (13 papers, 2016 to 2025). A tumor composed of atypical neoplastic, often pleomorphic cells that invade other tissues. "The positive associations with TMB and MSI suggest that P2RY6 may influence the immune response in these specific cancer types." (PMID 37880703, 2023). "P2RY6 is significantly upregulated in various cancer tissues, including HCC, potentially influencing immune-related pathways such as cytokine-cytokine receptor interactions." (PMID 39546272, 2025). "To further investigate the potential mechanisms of P2RY6 in various cancers, we analyzed the enrichment of P2RY6-related signaling pathways using the TCGA database and found significant correlations with multiple immune-related pathways." (PMID 37880703, 2023). "By comparing the expression level of P2RY6 in cancer and paracancerous tissues, we observed a significant difference between the two." (PMID 37880703, 2023). "To investigate the potential molecular functions of P2RY6 in various cancers, we performed gene cluster enrichment analysis." (PMID 37880703, 2023). "Based on the data obtained from the pan-cancer database, we conducted an evaluation of the mRNA expression level of P2RY6." (PMID 37880703, 2023). "As for genetics, the 11q13 region was reported to be involved in cancer development, as well as the P2RY6 gene positioned in the 11q13.4 region." (PMID 37465641, 2023). "Our analysis revealed a positive association between the expression of P2RY6 and immunosuppressive genes such as CD86, CD80, IL2RA, TGFB1, and LGALS9 in pan-cancer." (PMID 37880703, 2023). "Our analysis encompassed 47 common immune checkpoint genes, and we observed a strong correlation between the expression of P2RY6 and these genes in various types of cancers." (PMID 37880703, 2023). "Our findings indicate that P2RY6 exhibits significantly higher expression levels in various cancer tissues, particularly in LUAD." (PMID 37880703, 2023). "We hope that these findings will provide valuable references for future laboratory research and clinical applications of P2RY6 in cancer prognosis and immunotherapy." (PMID 37880703, 2023). "The data analysis revealed a significant difference in the expression level of P2RY6 in LUAD compared to other cancer tissues, with LUAD showing notably higher expression." (PMID 37880703, 2023). "Using the “pathological staging” module of the World Health Organization, we conducted an analysis to examine the correlation between the expression of P2RY6 and the pathological stage of cancer." (PMID 37880703, 2023). "Interestingly, we found that P2RY6 is closely related to the immunity of many cancers, especially LUAD." (PMID 37880703, 2023). "Additionally, we explored the immune effects of P2RY6 in cancer from other perspectives." (PMID 37880703, 2023). "Therefore, after analyzing several databases including GEPIA, Timer, Kaplan–Meier plotter, and TCGA, we speculate that P2RY6 may be a cancer-promoting gene, and its expression may be a valuable prognostic biomarker in cancer." (PMID 37880703, 2023).
neurodegenerative disease (4 papers, 2021 to 2024). A disorder of the central nervous system characterized by gradual and progressive loss of neural tissue and neurologic function. "Therefore, future research is pivotal to gain further insight in the diverse roles of P2RY6 during neuroinflammatory and neurodegenerative diseases and to determine how and in which context this pathway can be targeted." (PMID 36203578, 2022). "HSPs, including HSP90AA1, HSPA8 and DNAJB1 (all upregulated in the presence of P2RY6 antagonist) are key players in chaperone-mediated autophagy (CMA), a form of autophagy that is impaired in aging and neurodegenerative diseases." (PMID 36203578, 2022). "Based on our data and published literature, we propose that blocking of P2RY6-mediated signaling can indeed reduce neuroinflammation and might induce HSP expression and CMA activity, which are all considered advantageous during neurodegenerative diseases." (PMID 36203578, 2022).
P2RY6 also shares sentences with these, for which no sentence is quoted: atherosclerosis (9 papers); Hypertension (6); infection (6); gastric cancer (5); inflammatory bowel disease (5); Stroke (5); asthma (3); astrocytoma (3); breast carcinoma (3); gout (3); Insulin resistance (3); pulmonary fibrosis (3); Alzheimer disease (2); brain ischemia (2); colitis (2); epilepsy (2); glaucoma (2); ischemia (2); melanoma (2); pancreatic ductal adenocarcinoma (2); abdominal aortic aneurysm (1); acute myeloid leukemia (1); Alexander disease (1); allergic asthma (1); amyotrophic lateral sclerosis (1); aneurysm (1); arteriosclerosis (1); Atrophy (1); autoimmune disease (1); bladder overactivity (1).
A further 54 diseases each share a sentence with P2RY6 in 1 paper.